CPOX (coproporphyrinogen oxidase)
Description:
Catalyzes the aerobic oxidative decarboxylation of propionate groups of rings A and B of coproporphyrinogen-III to yield the vinyl groups in protoporphyrinogen-IX and participates to the sixth step in the heme biosynthetic pathway.
Synonyms: COX; CPO; CPX; HCP; HARPO
Tractability: Small molecule: a high-quality ligand is known. PROTAC: ubiquitination databases record sites on it; its protein half-life has been measured.
Target class: Enzyme; Oxidoreductase
Gene: Protein-coding gene on chromosome 3 (98,579,446 to 98,593,707, reverse strand). Ensembl gene ENSG00000080819.
Subcellular location: Mitochondrion intermembrane space
Subcellular location (Human Protein Atlas): Mitochondria
Pathways (Reactome):
Metabolism: Heme biosynthesis
Gene Ontology:
Molecular function: coproporphyrinogen oxidase activity; protein homodimerization activity; identical protein binding; structural constituent of eye lens
Biological process: heme B biosynthetic process; heme biosynthetic process; heme A biosynthetic process; porphyrin-containing compound biosynthetic process; response to arsenic-containing substance; response to insecticide; response to iron ion; response to lead ion; response to methylmercury
Cellular component: mitochondrion; cytoplasm; mitochondrial intermembrane space; membrane; mitochondrial inner membrane
Genetic constraint (gnomAD): Loss-of-function variants: 21 observed, 37.8 expected, observed/expected ratio (o/e) 0.56, 90% interval 0.39 to 0.8. The upper end of that interval is the gene's LOEUF score, 0.8, which puts it in group 3 of 6, group 1 being the genes least tolerant of losing a copy. Missense variants: 541 observed, 556.62 expected, observed/expected ratio (o/e) 0.97, 90% interval 0.9 to 1.04. Synonymous variants: 246 observed, 215.44 expected, observed/expected ratio (o/e) 1.14, 90% interval 1.03 to 1.27.
Gene-disease validity (ClinGen):
ClinGen rates the evidence that CPOX causes each of these diseases.
CPOX-related hereditary coproporphyria (semidominant): Definitive. A porphyria caused by monoallelic and biallelic variants in CPOX and presenting as a spectrum of disease (a semidominant inheritance pattern).
Homologues: Orthologues: chimpanzee CPOX (99% identical), macaque CPOX (95% identical), rabbit CPOX (89% identical), guinea pig CPOX (84% identical), pig CPOX (84% identical), dog CPOX (82% identical), rat Cpox (79% identical), mouse Cpox (79% identical), tropical clawed frog cpox (63% identical), zebrafish cpox (59% identical), Drosophila melanogaster Coprox (50% identical).
Diseases named in the same sentence as CPOX in open-access papers:
CPOX is named in the same sentence as 30 diseases in open-access papers, as found by Europe PMC text mining. Sharing a sentence is not in itself a finding about the gene and the disease. The quoted sentences say what the papers report.
hereditary coproporphyria (15 papers, 2014 to 2025). A form of acute hepatic porphyria characterized by the occurrence of neuro-visceral attacks and, more rarely, by the presence of cutaneous lesions. "Hereditary coproporphyria (HCP) is caused by a partial deficiency of coproporphyrinogen oxidase (CPOX), the sixth enzyme in the heme synthetic pathway." (PMID 35228944, 2022). "Hereditary coproporphyria (HCP) is a rare autosomal dominant disorder caused by a partial deficiency of coproporphyrinogen III oxidase (CPOX), and systemic lupus erythematosus (SLE) is an autoimmune disease with a strong genetic predisposition." (PMID 35669728, 2022). "Rare inherited mutations in CPOX cause the autosomal dominant disease coproporphyria, which, like other porphyrias, is associated with low hemoglobin levels and anemia." (PMID 24704585, 2014). "Hereditary coproporphyria is an autosomal dominant disorder that occurs as a result of deficiency of the mitochondrial enzyme coproporphyrinogen oxidase (CPOX)." (PMID 25372274, 2014). "Hereditary coproporphyria (HCP) is an acute hepatic disorder that stems from a dominantly inherited mutation in the gene encoding the sixth haem enzyme coproporphyrinogen III oxidase (CPOX)." (PMID 28600349, 2017). "In humans, mutations in the CPOX gene that diminish enzyme activity can be a cause of hereditary coproporphyria (HCP; OMIM #121300), a genetically dominant disease with incomplete penetrance." (PMID 36967721, 2023). "Based on the early manifestation initially a harderoporphyria, which is the neonatal-onset form of homozygous hereditary coproporphyria, was discussed, but the molecular genetic analysis of the CPOX gene was normal." (PMID 40114189, 2025). "In humans, mutations in the coproporphyrinogen oxidase (CPOX) gene can result in hereditary coproporphyria (HCP), characterized by high levels of coproporphyrin excretion in the urine and feces, as well as acute neurovisceral and chronic cutaneous manifestations." (PMID 36967721, 2023). "Hereditary coproporphyria (HCP) is a rare disorder caused by a deficiency of an enzyme, coproporphyrinogen oxidase, in the heme synthetic pathway." (PMID 35228944, 2022). "Hereditary coproporphyria is much less frequent than AIP and is due to a deficiency of coproporphyrinogen oxidase activity." (PMID 25525547, 2014). "Hereditary coproporphyria was confirmed by plasma porphyric emission spectrum (positive at 619 nm), 20-fold increases in urinary and faecal excretion of coproporphyrin (isomers I < III) and a mutation in the coproporphyrinogen oxidase gene (p.L94P)." (PMID 36757574, 2023). "Hereditary coproporphyria (HCP) is a kind of acute hepatic porphyria (AHP) and a rare autosomal dominant disorder caused by genetic mutation in coproporphyrinogen III oxidase (CPOX)." (PMID 35669728, 2022).
porphyria (7 papers, 2014 to 2026). Porphyria is a group of diseases in which substances called porphyrins build up, negatively affecting the skin or nervous system. "Mutations or abnormalities in the CPOX gene can disrupt the heme biosynthesis pathway, potentially leading to genetic disorders such as porphyria." (PMID 38259465, 2023). "These SNPs are located in genes known to cause different kinds of porphyria, e.g. UROS and CPOX genes." (PMID 31824661, 2019). "At the Royal Prince Alfred Hospital in Australia, a cohort of 36 porphyria patients of European descent and their family members were evaluated for clinical history, biochemical profile and detection of pathogenic mutations in haem biosynthetic pathway genes (HMBS, CPOX, PPOX or FECH)." (PMID 27507172, 2016). "Together, these results identify multiple metabolite- and toxin-dependent mechanisms that converge on CPOX inhibition, offering new insights into the pathophysiology of ALADP, among other porphyrias, lead intoxication, and HT1." (PMID 41677324, 2026).
variegate porphyria (6 papers, 2014 to 2025). Variegate porphyria is a form of acute hepatic porphyria characterized by the occurrence of neuro-visceral attacks with or without the presence of cutaneous lesions. "In humans, accumulation of porphyrins due to hereditary defects of either protoporphyrin oxidase or coproporphyrinogen oxidase are known as human variegate porphyria disease and hereditary coproporphyria." (PMID 33462229, 2021).
glioma (5 papers, 2020 to 2025). A benign or malignant brain and spinal cord tumor that arises from glial cells (astrocytes, oligodendrocytes, ependymal cells). "Another enzyme whose expression is directly related to the fluorescence of PpIX in glioma cells is coproporphyrinogen oxidase (CPOX)." (PMID 40430928, 2025). "According to our data, we found distinct increases in the 5-ALA metabolizing enzymes CPOX, PPOX, and FECH and decreases in the PpIX exporting transporter ABCG2 on protein level in fluorescing glioma samples." (PMID 35665365, 2022). "To this end, we compared the mRNA as well as protein expression levels of CPOX, PPOX, FECH and ABCG2 in glioma tissue samples with presence of strong 5-ALA induced fluorescence during surgery to non-fluorescing glioma samples." (PMID 35665365, 2022). "It is thus of note that in contrast to the documented alterations in CPOX mRNA expression in both directions for verified fluorescent cell lines, our study found an almost identical expression in WHO grade II and IV gliomas." (PMID 32722247, 2020). "The results of this study demonstrate that protein levels of the investigated heme biosynthesis factors do not correlate with mRNA expression in gliomas in most cases (CPOX, PPOX, and FECH)." (PMID 35665365, 2022). "CPOX is the gene previously most controversially studied in fluorescent vs. non-fluorescent gliomas." (PMID 32722247, 2020).
acute intermittent porphyria (2 papers, 2018 to 2024). Acute intermittent porphyria is the most frequent and the most severe form of the acute hepatic porphyrias. "Acute intermittent porphyria (AIP), HCP, and VP are inherited in an autosomal dominant way and result from a deficiency of one of the enzymes, hydroxymethylbilane synthase (HMBS), coproporphyrinogen oxidase (CPOX), and protoporphyrinogen oxidase (PPOX), respectively." (PMID 29553924, 2018).
acute porphyria (2 papers, 2013 to 2023). "Gene dosage analysis has earlier been shown to increase the diagnostic sensitivity for the two other acute porphyrias (AIP and HCP) and large deletions have been reported for the HMBS and CPOX genes, respectively." (PMID 23324528, 2013).
brain tumor (2 papers, 2011 to 2022). "We found that the level of mRNA encoding coproporphyrinogen oxidase (CPOX) was remarkably increased in malignant brain tumors that exhibited strong fluorescence of PpIX after 5-ALA administration." (PMID 24310600, 2011). "Thus, it has been concluded that the elevated levels of CPOX protein as well as its mRNA are one of the major mechanisms underlying the ALA-induced PpPIX fluorescence in malignant brain tumors." (PMID 24310600, 2011). "The high mRNA level of CPOX expression was significantly well correlated with the phenotype of strong 5-ALA induced fluorescence and accumulation of PpIX in malignant brain tumors." (PMID 24310600, 2011).
malignant glioma (2 papers, 2011 to 2023). A grade III or grade IV glioma arising from the central nervous system. "CPOX catalyzes oxidation of coproporphyrinogen III to PpIX, and upregulation was shown in malignant gliomas and correlated with intraoperative tumor fluorescence, which matched our observations in meningiomas." (PMID 36612300, 2023). "Taken together, it is strongly suggested that both up-regulation of CPOX and down-regulation of ABCG2 are important factors involved in the high accumulation of PpIX in certain cancer cells, including malignant glioma cells." (PMID 24310600, 2011).
asthma (1 paper, 2012). "Some of these genes were altered sex specifically in the placenta of asthmatic women, including GAPDH which was only altered in males, while MDH2, COMT, and CPOX were decreased in female placentae of pregnancies complicated by asthma." (PMID 22830026, 2012). "The presence and absence of inhaled glucocorticoid use for asthma treatment during pregnancy also influenced mitochondrial gene expression, with MDH2, COMT, and CPOX gene expression being increased in placentae of females whose mothers' used these inhaled steroids during pregnancy." (PMID 22830026, 2012).
meningioma (1 paper, 2023). A generally slow growing tumor attached to the dura mater. "Protein expression of ABCB6, ABCG2, FECH and CPOX was found in meningioma tissue and was correlated with fluorescence (p < 0.05, each), whereas this was not confirmed for mRNA expression." (PMID 36612300, 2023). "ABCB6, ABCG2, FECH and CPOX are expressed in meningioma tissue and are related to fluorescence." (PMID 36612300, 2023). "In samples from the bulk tumor, the median expression scores for ABCB6, ABCG2, FECH and CPOX were 9 (range: 2–12), 8 (range: 3–12), 9 (range: 1–12) and 9 (range: 1–12), respectively, and expression was similar comparing grade 1 and 2/3 meningiomas (p > 0.05 for each)." (PMID 36612300, 2023).
ovarian carcinoma (1 paper, 2023). A malignant neoplasm originating from the surface ovarian epithelium. "The expression of ALAS2, HMBS, and FXN involved in iron utilization was associated with improved OS in ovarian cancer, whereas the expression of ALAD, ALAS1, and CPOX in this process was associated with poor OS in ovarian cancer." (PMID 38186569, 2023). "For iron utilization, a lower expression of CIAO1 and CPOX was associated with a more advanced stage of ovarian cancer." (PMID 38186569, 2023).
preeclampsia (1 paper, 2023). Preeclampsia is a hypertensive disorder of pregnancy that is characterized by new-onset hypertension with proteinuria presenting after 20 weeks of gestation, and depending on mild or severe forms may initially present with severe headache, visual disturbances, and hyperreflexia. "Then, we performed LASSO and SVM-RFE and identified three critical diagnostic genes for preeclampsia, including CPOX, DEGS1 and SH3BP5." (PMID 38259465, 2023). "Compared to normal samples, preeclampsia samples showed markedly elevated expression of CPOX, DEGS1, and SH3BP5, as determined by RT-PCR." (PMID 38259465, 2023). "Then, we developed a novel diagnostic model using CPOX, DEGS1, and SH3BP5 and it showed a strong ability in screening preeclampsia samples from normal samples." (PMID 38259465, 2023). "The high expression of CPOX, DEGS1, and SH3BP5 may be associated with the pathogenesis of preeclampsia." (PMID 38259465, 2023). "In this study, we found that the expressions of CPOX, DEGS1 and SH3BP5 were highly expressed in preeclampsia samples in GSE44711 and GSE75010 datasets and our cohort." (PMID 38259465, 2023). "Importantly, the results of RT-PCR confirmed the expressions of CPOX, DEGS1 and SH3BP5 were distinctly increased in preeclampsia samples compared with normal samples." (PMID 38259465, 2023). "To date, the function of CPOX in preeclampsia has not been investigated." (PMID 38259465, 2023).
prostate carcinoma (1 paper, 2024). A carcinoma that arises from epithelial cells of the prostate gland. "For instance, CPOX autoantibodies were identified as discriminatory markers between prostate cancer and healthy tissues." (PMID 38652547, 2024).
cancer (6 papers, 2011 to 2024). A tumor composed of atypical neoplastic, often pleomorphic cells that invade other tissues. "To date, most studies looking at alterations in cancer and their impact on PpIX synthesis have focussed on the mitochondrial enzymes in the haem biosynthesis pathway, coproporphyrinogen oxidase and ferrochelatase." (PMID 31406300, 2019). "CPOX encodes the enzyme coproporphyrinogen oxidase, which is involved in the biosynthesis of heme and has not been studied much in the context of cancer." (PMID 38291365, 2024). "Further investigation may also help to shed light on the regulation of enzymes such as CPOX and their role in the enhanced PpIX accumulation in cancer." (PMID 31406300, 2019). "Photodynamic diagnosis, a technique used for the cancer diagnosis, has also shown the reduced accumulation of metabolized photosensitizer PpIX from 5-ALA, due to decreased expression of protoporphyrinogen IX oxidase (PPOX) and coproporphyrinogen oxidase (CPOX) enzymes involved in PpIX synthesis." (PMID 33203053, 2020).
tumor (6 papers, 2019 to 2025). "Additionally, CEACAM1 and CPOX were highly upregulated in the tumor cluster compared to the stroma cluster." (PMID 38291365, 2024). "As expected, most tumor samples displayed expression of ABCB6, ABCG2, FECH and CPOX in our study, and expression was strongly correlated with fluorescence." (PMID 36612300, 2023). "Clinical samples showed significant downregulation of the following genes: CPT2, ACAA2, HPGD and ALDH3A2, while the expression of ENO2, TDO2, CPOX, ACADL and PTPRG was significantly upregulated in the tumor tissue (p < 0.01)." (PMID 36230866, 2022). "Notably, unspecific low-to-moderate expression of ABCB6 (median score 8, range: 8–9), ABCG2 (median score 3, range: 1–4), FECH (median score 4, range: 1–8) and CPOX (median score: 1, range: 0–1) was also found in all nine fluorescent cortex samples lacking tumor invasion." (PMID 36612300, 2023).
CPOX also shares sentences with these, for which no sentence is quoted: bladder (2 papers); Acute hepatic porphyria (1); anemia (1); autoimmune disease (1); autosomal dominant disease (1); genetic disorders (1); harderoporphyria (1); Insulin resistance (1); metabolic disorders (1); neurodevelopmental disorder (1); Obesity (1); osteopetrosis (1); sarcoma (1); systemic lupus erythematosus (1); thyroid cancer (1).